BRCA1 (BRCA1 DNA repair associated)
Diseases named in the same sentence as BRCA1 in open-access papers (continued):
Sharing a sentence is not in itself a finding about the gene and the disease.
ovarian carcinoma (continued). "An additional mechanism of resistance relevant in ovarian carcinoma includes restoration of homologous recombination (HR) in tumor cells originally bearing mutations in the BRCA1 or BRCA2 genes." (PMID 39430244, 2024). "Such uterine cancers exhibit similar molecular and morphological characteristics, indicating the potential of a connection to hereditary breast and ovarian cancer and the BRCA1 mutation." (PMID 38297203, 2024). "High lead blood levels are associated with an increased risk of ovarian cancer risk in BRCA1 carriers." (PMID 38732616, 2024). "A well-established clinical example in this regard is the use of PARP inhibitors in BRCA1 or BRCA2 mutated ovarian cancers." (PMID 38475864, 2024). "Patients in dose‐expansion cohort 1 (ovarian cancer) or cohort 2 (TNBC) were required to have historical or central BRCA1/2 mutation or HRD+ for enrollment." (PMID 38970256, 2024). "Our results demonstrated a modest and non-significant association between a low blood zinc level and an increased risk of ovarian cancer in unaffected BRCA1 carriers." (PMID 38790714, 2024). "Ovarian cancer risk factors were significantly correlated with the community-type O cervicovaginal microbiota, including age and BRCA1 germline mutations." (PMID 38877504, 2024). "Instead of targeting DDX41 itself, we can target DDX41's SL partner, analogous to the case where PARP-1 inhibitors are used to treat BRCA1/2-mutated breast and ovarian cancer patients." (PMID 38348889, 2024). "One such approach is whole exome sequencing (WES), which can identify genetic variants associated with breast and ovarian cancer susceptibility beyond BRCA1 and BRCA2 mutations." (PMID 38660159, 2024). "Blood molybdenum level can be also an attractive target for clinical trials aimed to decrease ovarian cancer risk on BRCA1 carriers." (PMID 39300540, 2024). "Approximately 14–24% of individuals diagnosed with ovarian cancer harbor BRCA1/BRCA2 mutation and are often hereditary." (PMID 38796525, 2024). "We previously observed a high rate of heterozygous BRCA1/2 mutations in ovarian cancer cell lines suggesting evidence of selective pressure against cells with defects in DNA repair." (PMID 38940864, 2024). "It is one of the few successes of clinical intervention for ovarian cancer patients that screening for BRCA1/2 mutations is now routinely used in clinical practice." (PMID 38391958, 2024). "Large-scale studies from Apulia demonstrated that the BRCA1 c.5266dupC variant represents 54.9% of BRCA1 carriers among 2.026 hereditary breast and ovarian cancer patients." (PMID 39590369, 2024). "In this prospective study of 989 BRCA1 mutation carriers we observed a strong association between blood molybdenum level and the risk of ovarian cancer." (PMID 39300540, 2024). "The presence of BRCA1/2 mutations in the ctDNA of ovarian cancer patients was observed, and these patients showed a positive response to targeted therapy with PARP1 inhibitors." (PMID 39492906, 2024). "Resistance to therapy, specifically platinum/PARP inhibitors, was found to be related to reversion mutations of BRCA1/2 in the plasma of patients with ovarian cancer." (PMID 39492906, 2024). "The BRCA1 gene codes for a tumor suppressor whose mutations in humans were associated with a predisposition to breast and ovarian cancers due to abnormal cell cycle pathways." (PMID 41262543, 2024). "Approximately 23% of all ovarian cancers have a hereditary component, with pathogenic variants in BRCA1/2 being the most common among epithelial ovarian cancers." (PMID 39061202, 2024). "BRCA1/2 mutation carriers were significantly younger at diagnosis and more likely to have a family history of breast/ovarian cancer." (PMID 38689097, 2024). "In individuals with a hereditary predisposition to breast and ovarian cancer, specifically carriers of the BRCA1/2 PVs/LPVs, early and intensive screening is of paramount importance due to the early age of disease onset." (PMID 39796670, 2024).
ovarian carcinoma (continued). "For example, mutation in BRCA1 or BRCA2 tumor suppressor genes predispose individuals at risk for developing ovarian cancer and breast cancer." (PMID 38796525, 2024). "The results also mirrored our general knowledge concerning the genetic background of hereditary breast and ovarian cancer, as variants in either one of the BRCA1 and BRCA2 genes proved to be the most common cause among our patients with 41.5%." (PMID 39148954, 2024). "It cannot be assumed that the impact of HRT on the recurrence of ovarian cancer in BRCA1/2-pV carriers or pV-carriers in other risk genes for ovarian cancer differs significantly from that of women with sporadic ovarian cancer." (PMID 39259360, 2024). "Performing a salpingo-oophorectomy as a preventive measure in women with BRCA1 or BRCA2 gene mutations has a substantial effect by drastically reducing the risk of ovarian carcinoma and significantly lowering the overall mortality." (PMID 39338246, 2024). "For example, women who have inherited BRCA1 mutations have a lifetime risk of developing ovarian cancer ranging from 40% to 60%, while those with BRCA2 mutations have a lifetime risk of 11% to 27%." (PMID 38817903, 2024). "Out of the seven patients who had both breast and ovarian cancer (metachronous), five had undergone genetic testing, with P/LP variant found in all five patients (four BRCA1 and 1 BRCA2)." (PMID 38439815, 2024). "Deficiencies in the BRCA1 tumor suppressor gene are the main cause of hereditary breast and ovarian cancer." (PMID 38769345, 2024). "For example, germline BRCA1 haploinsufficiency poses a major risk of developing breast and ovarian cancer." (PMID 38247798, 2024). "The identification of different BRCA1-associated ovarian cancer subtypes, such as high-grade serous ovarian cancer, further emphasizes the importance of understanding the genetic landscape to develop targeted therapeutic approaches." (PMID 38543119, 2024). "Oral contraceptives significantly reduce ovarian cancer risk in BRCA1/2-pV carriers or pV-carriers in other risk genes for breast and ovarian cancer." (PMID 39259360, 2024). "This approach allows for the comprehensive assessment of single nucleotide variants and CNVs in BRCA1/2, alongside other high and moderately penetrant genes associated with breast and ovarian cancer." (PMID 38566764, 2024). "Mutations in the breast cancer susceptibility gene 1 (BRCA1) are associated with an increased risk of triple-negative breast cancer and ovarian cancer, both of which pose significant challenges in treatment due to their aggressive nature." (PMID 38993666, 2024). "We therefore suggested that LYN is an oncogene in the context of BRCA1 loss, and a potential therapeutic target in BRCA1 loss-of-function breast and ovarian cancers." (PMID 38149669, 2024). "Prior investigations in Chile among individuals with a personal or familial history of breast and ovarian cancer have revealed varying frequencies of pathogenic (P) variants in BRCA1/2, ranging between 7% and 17%." (PMID 38566764, 2024). "Several studies have shown that, from the perspective of susceptibility genes, BRCA1/2 is significantly associated with the occurrence of ovarian cancer." (PMID 38817903, 2024). "When evaluating ovarian cancer risk by the age of 80 years for BRCA1 and BRCA2 carriers, the PRSHGS (22 SNPs predicting high-grade serous OC) at the 5th and 95th percentiles showed risks of 30% and 59%, and 10% and 28%, respectively." (PMID 38397209, 2024). "For instance, women with a BRCA1 mutation have a lifetime risk of 55–72% of developing BC and 39–44% of developing ovarian cancer." (PMID 39796670, 2024). "Surprisingly, it was discovered that women with the BRCA1 mutation had Lactobacillus-depleted cervicovaginal microbiota even before the onset of ovarian cancer." (PMID 38275400, 2024).
ovarian carcinoma (continued). "In 1994, through extensive research on families with a history of early-onset breast and/or ovarian cancer, the discovery of the connection between BRCA1 and BRCA2 genes and the development of cancer risk was made." (PMID 38397209, 2024). "For example, in ovarian cancer cases, BRCA1/2 mutations were associated with positive response rates toward platinum-based chemotherapy alongside PARP inhibitors." (PMID 38392565, 2024). "For ovarian cancer, the cumulative risks by age 80 years are 44% for BRCA1 mutation carriers and 17% for BRCA2 mutation carriers." (PMID 38717180, 2024). "Since the identification of BRCA1 nearly 30 years ago unfortunately little has changed for definitive ovarian cancer risk-reduction." (PMID 38539519, 2024). "Given the earlier age of ovarian cancer onset linked with a germline BRCA1 mutation, efforts to minimize cancer-initiating events are needed particularly in the context for those declining or deferring surgery." (PMID 38539519, 2024). "For example, cases have been reported where chemotherapy for ovarian cancer led to regression of vestibular schwannoma, suggesting shared biological mechanisms such as BRCA1 mutations influencing tumor behavior in both conditions." (PMID 39621164, 2024). "Given that approximately 15% of ovarian cancers are heritable through BRCA1/2 mutation, our results are slightly lower compared to the current literature on this topic." (PMID 39061202, 2024). "Risk‐reducing salpingo‐oophorectomy (RRSO) is recommended by international guidelines in women with BRCA1/2 germline pathogenic variants (PV) to prevent ovarian cancer." (PMID 39624976, 2024). "Owing to limitations in sample size, sampling regions, and differences in detection platforms, current studies can’t comprehensively and accurately profile the BRCA1/2 mutations of ovarian cancer in the Chinese population." (PMID 38817903, 2024). "In the present study, we used publicly available datasets to perform a comprehensive investigation to unravel the molecular events driving resistance to PARPi therapy in BRCA1-deficient ovarian cancer." (PMID 39408764, 2024). "Clinical trials have demonstrated promising response rates among ovarian cancer patients with BRCA1/2 germline mutation receiving PARP inhibitors." (PMID 38561819, 2024). "This study aimed to investigate the patterns of cancer risk-reducing strategies recommended for unaffected BRCA1/2 mutation carriers with higher risks of breast and ovarian cancer." (PMID 39590130, 2024). "The link between BRCT domain mutations in BRCA1 and susceptibility to ovarian cancer becomes clear when considering the complex relationship between genetic alterations and disease manifestation." (PMID 38543119, 2024). "The study included patients with advanced (FIGO stage III or IV) epithelial ovarian cancer and BRCA1 and/or BRCA2 mutations." (PMID 39590126, 2024). "Therapeutic strategies combining PARPi and immunotherapy have raised interest in BRCA1/2-mutated ovarian cancers." (PMID 38544832, 2024). "Nowadays, tumor tests to analyze DNA in tumor cells from epithelial tubal/ovarian cancers (EOCs) are performed in many centers to detect tumor pathogenic variants (TPVs) in the BRCA1/2 genes." (PMID 38730634, 2024). "The genesis of HRD in ovarian cancer cells results from mutations in important genes, primarily BRCA1 or BRCA2." (PMID 39360040, 2024). "The impact of PARPi and BRCA1 mutations on the activation of immune-related pathways was studied using ovarian cancer cell lines, RNA sequencing, and immunofluorescence analysis." (PMID 39669575, 2024). "BRCA1/2 pathogenic variant carriers do not only face a high risk of breast, but also of ovarian cancer." (PMID 38892081, 2024). "Genetic counseling is recommended for individuals with BRCA1/2 mutations because of the well-documented advantages of surveillance, chemoprevention and risk-reducing surgeries in managing breast and ovarian cancer." (PMID 39421188, 2024).
ovarian carcinoma (continued). "This study aimed to analyze the patterns of cancer risk-reducing strategies used by unaffected BRCA1/2 mutation carriers with a family history of breast or ovarian cancer who were included in the KOHBRA study." (PMID 39590130, 2024). "It is of much import halachically that the risk for ovarian cancer becomes significant after 35–40 for BRCA1 mutation carriers and 5–10 years later for BRCA2 mutation carriers." (PMID 38717180, 2024). "Such mutations can disrupt the normal function of the BRCA1 protein, increasing the risk of hereditary breast and ovarian cancer." (PMID 38543119, 2024). "It is well known that breast and ovarian cancer cells with BRCA1/2 mutations are defective in HR and highly sensitive to PARPi5–8." (PMID 38383600, 2024). "The ovarian cancer risk guidelines recommend risk-reducing salpingectomy-oophorectomy (RRSO) for BRCA1 mutation carriers between the ages 35 and 40 years, or on completion of childbearing years." (PMID 38717180, 2024). "Despite its efficacy, the SOLO1 study focused exclusively on patients with BRCA1/2 mutations, which are present in only 5–15% of ovarian cancer cases." (PMID 39590126, 2024). "Ovarian cancer with BRCA1/2 mutations shows higher immune infiltrates, including CD3+ and CD8+ T-cells, high PD-1 expression, and an association with BRCA1 mutation or loss of function, suggesting possible suitability for immune checkpoint blockade therapy." (PMID 38543119, 2024). "Ovarian cancers with BRCA1 alterations (germline and somatic mutations in 12% of cases, DNA hypermethylation in 11% of cases) and BRCA2 alterations (germline and somatic mutations in 11% of cases), are associated with homologous recombination deficiency (HRD)." (PMID 38952544, 2024). "Breast and ovarian cancers are prevalent worldwide, with genetic factors such as BRCA1 and BRCA2 mutations playing a significant role." (PMID 38660159, 2024). "Carriers of pathogenic variants in BRCA1/2 genes are known to have a high risk of developing BC and ovarian cancer." (PMID 38892081, 2024). "Whole-exome sequencing of 31 human OS tumors found that most contained loss of heterozygosity signatures similar to that of BRCA1/2 inactivation in breast and ovarian cancers." (PMID 38362299, 2024). "Women with an inherited BRCA1 mutation have a lifetime risk of breast cancer up to 80% and a risk of ovarian cancer up to 40%." (PMID 39300540, 2024). "For example, poly(ADP-ribose) polymerase (PARP) inhibitors in breast cancer gene 1 (BRCA1) or BRCA2 mutated ovarian cancers exploit this cancer intrinsic vulnerability and lead to synthetic lethal interactions with clinical relevance." (PMID 38475864, 2024). "Further research is warranted to confirm these findings and explore interventions targeting molybdenum levels as a preventive measure for ovarian cancer in BRCA1 mutation carriers." (PMID 39300540, 2024). "In our registry, patients with both breast and ovarian cancers were more likely to carry a BRCA1 mutation (24.7%) than a BRCA2 mutation (10.8%)." (PMID 39061189, 2024). "There have been several studies carried out in Romania to evaluate the mutational status of BRCA1/2 in the context of both BC and combined breast and ovarian cancer." (PMID 39796670, 2024). "Germline BRCA1 or BRCA2 mutations yield ovarian cancer, most often HGSOC, with a lifetime unmitigated risk of 30–70%." (PMID 38352443, 2024). "Germline pathogenic variants in BRCA1 predispose carriers to significantly elevated risks of breast and ovarian cancers, but the relationship between BRCA1 and CRC susceptibility is less clear." (PMID 38063999, 2024).
ovarian carcinoma (continued). "This is the first study to demonstrate an association between blood iodine levels in BRCA1 carriers and breast and ovarian cancer risk." (PMID 38892720, 2024). "Similar findings have been reported in studies involving individuals with ovarian cancer, where patients with advanced high-grade serous ovarian cancer and BRCA1/2 mutations exhibited extended progression-free survival and higher overall survival rates." (PMID 38809921, 2024). "The lifetime risk of breast and ovarian cancer increases substantially for individuals with mutations in BRCA1/2." (PMID 39590130, 2024). "The MEDIOLA phase II clinical trial investigated the combination of olaparib and durvalumab in BRCA1/2-mutated platinum-sensitive recurrent ovarian cancer patients." (PMID 38544832, 2024). "Mutations in breast cancer gene 1 and 2 (BRCA1 and 2) increase the risk of developing ovarian cancer due to dysregulation of DNA damage repair." (PMID 39272943, 2024). "As a result, constitutive MGMT promoter methylation, like BRCA1, is a potential diagnostic biomarker for breast and ovarian cancer risk." (PMID 38542081, 2024). "Poly (ADP‐ribose) Polymerase inhibitors (PARPi) have demonstrated remarkable clinical efficacy in treating ovarian cancer (OV) with BRCA1/2 mutations." (PMID 39412086, 2024). "We also recommend a prospective study to assess the association between BRCA1 protein expression with overall survival and response to different chemotherapy modalities in ovarian cancer patients in Ugandan patients." (PMID 39502381, 2024). "Approximately 50% of patients diagnosed with ovarian cancer harbor tumors with mutations in BRCA1, BRCA2, or other genes involved in homologous recombination repair (HR)." (PMID 39408764, 2024). "Intriguingly, one study proposed the potential interplay between BRCA1/2 mutations and the cervicovaginal microbiome, which influences the risk of ovarian cancer." (PMID 38541242, 2024). "We report in this study that loss of function in BRCA1 or BRCA2 results in distinct responses to Wnt signaling in ovarian cancer cells." (PMID 39028933, 2024). "In a previous study we profiled a large panel of 41 ovarian cancer cell lines for their BRCA1/2 mutation and BRCA1 methylation status." (PMID 38940864, 2024). "The reported germline BRCA1/2 mutation prevalence in ovarian cancer is ranged from 5.6% to 29.3%, with the highest frequency in Ashkenazi Jews25." (PMID 38509102, 2024). "In both groups, there was a stronger correlation seen in younger persons between the community type O microbiota and the status of ovarian cancer or BRCA1 mutation." (PMID 38877504, 2024). "There are only one case–control study and one retrospective cohort study on the association between HRT and the risk of ovarian cancer in BRCA1/2-pV carriers." (PMID 39259360, 2024). "Poly (adenosine diphosphate [ADP]–ribose) (PARP) inhibitors were the first approved cancer drugs that specifically targeted the DNA damage response in BRCA1/2 mutated breast and ovarian cancers." (PMID 38561819, 2024). "Pathogenic variants within BRCA1/2 genes elevate the risk of both breast and ovarian cancers and give rise to distinct clinical phenotypes." (PMID 38966174, 2024). "The purpose of this study was to evaluate RB1 expression and survival across ovarian carcinoma histotypes and how co-occurrence of BRCA1 or BRCA2 (BRCA) alterations and RB1 loss influences survival in tubo-ovarian high-grade serous carcinoma (HGSC)." (PMID 38837893, 2024). "Characterizing the impact of novel VUS within BRCA1 Exon 11 mutations is thus critical for better understanding the genetic predisposition to breast and ovarian cancers of individuals." (PMID 38786046, 2024). "The mean cumulative risk of having ovarian cancer with BRCA1 pathogenic mutation is 40% [95% confidence interval (CI): 35–46%], and 18% (95% CI: 13–23%) for patients carrying BRCA2 mutations." (PMID 38540206, 2024).